TNF (tumor necrosis factor)
Diseases named in the same sentence as TNF in open-access papers (continued):
Sharing a sentence is not in itself a finding about the gene and the disease.
cancer (continued). "One meta-analysis of 26 RCTs varying from durations of 8–104 weeks and offering structured exercise interventions for cancer survivors investigated exercise’s effect on cytokine levels, including CRP and TNF-α, and showed decreased pro-inflammatory markers with exercise across all cancer types." (PMID 41546786, 2026). "Normal B and cancer 1 clusters shared inflammatory markers CCL2, TNFRSF12A, and IL1R1, pathways including TNFα, IL, and Myc signaling, and activity of inflammation, hypoxia, and lipid metabolism–associated transcription factors NFATC2, ARNT, PPARA, and PPARGC1A." (PMID 40215177, 2025). "Recent studies have shown that TAMs play an important role in immune-mediated cancer control through the secretion of multiple cytokines, including IL-6, IL-10, transforming growth factor β (TGF-β), tumor necrosis factor α (TNF-α), C-C chemokine motif ligand 18 (CCL18) and CCL22." (PMID 40369674, 2025). "Virtually no Annexin V positivity was detected in preparations containing only cancer cells with or without TAP1/2 silencing or after pre-incubation with IFNγ ± TNFα (e.g. (T) 1: (E) 0)." (PMID 40091029, 2025). "In agreement with data from our study, preclinical cancer cachexia studies consistently show significant overexpression of Atrogin1 and MuRF1 in skeletal muscle tissue of cachectic animals and C2C12 immortalized mouse myoblast cells treated in vitro with TNFα." (PMID 40558549, 2025). "Another study investigated the combination of anti-PD-1 with an adenovirus engineered to deliver tumor necrosis factor-alpha (TNF-α) and IL-2 in a mouse model of NSCLC: a reduction in cancer growth and an increased number of cytotoxic TILs were noticed, highlighting the potential of this approach." (PMID 39859299, 2025). "At the clinical level, previous meta-analyses have provided preliminary evidence that exercise can improve common metabolic disturbances in cancer patients, including blood glucose, insulin, and triglycerides, as well as inflammatory markers such as IL-6, C-reactive protein (CRP), and TNF-α." (PMID 40895542, 2025). "major extracts act against GC through the TNF and T-cell receptor signaling pathways by the binding of its characteristic saponins to the core targets TNF and CASP3 in those two signaling pathways, which are highly important in cancer and inflammation." (PMID 40573220, 2025). "The recombinant pDNA that was used co-expressed the tumor necrosis factor-α (TNF-α) and the herpes simplex virus thymidine kinase (HSV-TK), which leads to cancer cell apoptosis while sparing healthy cells through a process called suicide gene therapy, first described by Moolten." (PMID 40227824, 2025). "The hypoxic obese PRAT microenvironment may promote cancer progression by hypoxia-induced factor 1α (HIF-1α) signaling activation and upregulation of CCL2, TNF-α, IL-10, IL-8, and IL-6 pro-inflammatory cytokine expression via NF-κB-pathway stimulation." (PMID 40227577, 2025). "These transcription factors then enter the nucleus to induce the expression of type I interferon (IFN-I) and other cytokines, such as tumor necrosis factor (TNF), interleukin-1β (IL-1β), and IL-6, which are capable of directly eradicating cancer cells or indirectly promoting antitumor immunity." (PMID 40577452, 2025). "Additionally, polysaccharides isolated from Sargassum fusiforme stimulated immune responses, including tumor necrosis factor (TNF)-α secretion in splenocytes, thereby contributing to their anti-cancer effects." (PMID 39852540, 2025). "In cancer cells, VDR expression increased significantly, while TNFα remained unchanged." (PMID 41444742, 2025). "These EVs exhibit an oncogenic potential, regardless of the presence of cancer cells and associated factors, including IL-6, TNF-α, and TGF-β with de novo MMP-9 and TNF-α expression." (PMID 40243783, 2025).
cancer (continued). "The interaction between time and cancer type was not significant, F (2, 47.1) = 0.99, p = 0.381, indicating that the pattern of TNF-α changes over time was similar for both cancer groups." (PMID 41020868, 2025). "Gene ontology (GO) analysis of the downregulated genes indeed gave regulation of transcription as the most prominent effect, with several pathways related to normal tissue repair and cancer cell survival and proliferation (response to FGF and TNF, response to wounding, angiogenesis) being affected." (PMID 39508147, 2025). "To do this, we performed a wound-healing assay to determine whether TNF EVs could promote the migratory behavior of MCF-7 cells, a key step in cancer metastasis." (PMID 40567500, 2025). "Compared to UC patients without a history of cancer, UC patients who developed cancer were less likely to report treatment with anti-TNFα (56% vs. 11%, p < 0.001)." (PMID 40361323, 2025). "Inflammatory factors such as TNF-α play a crucial role in stimulating NK cells through PTT, establishing a foundation for the positive correlation observed between favorable prognosis and overall survival across several cancer types." (PMID 40688079, 2025). "In the regulation of sensitivity of cancer cells to T cell-mediated killing, positive selection was found in DNA Binding transcription factor activity, IFNγ signaling, necroptosis, RIPK1-mediated necrosis, and the TNF pathway." (PMID 39868264, 2025). "Lymphocytes can suppress cancer cell growth by secreting cytokines, such as IFN-γ or TNF-α." (PMID 40666098, 2025). "In cancer patients, MCP-1 levels are positively correlated with both VEGF and TNF-α concentrations." (PMID 41583457, 2025). "Among other important pathways and processes are apoptosis, HIF-1, mTOR, TNF, JAK-STAT, VEGF, and FoxO signaling, and pathways named after several cancer types and other diseases and infections (e.g. Epstein-Barr and Kaposi sarcoma-associated herpesvirus virus infections)." (PMID 40375077, 2025). "Notably, GO and KEGG analysis of H4K79la-related promoter peak genes revealed enrichment in glucose metabolic process, cell cycle, focal adhesion, and cancer-related signaling pathways, such as Wnt, PI3K-Akt, MAPK, and TNF pathways." (PMID 40849487, 2025). "EGCG decreased IL6 expression in monolayer cells but not in spheroids.While EGCG’s downregulation of IL6 and TNF in inflammationmodels and cancer cells is documented, its impact in spheroids is a novel exploration." (PMID 40821580, 2025). "Additionally, many cytokines and growth factors, including vascular endothelial growth factor (VEGF), fibroblast growth factor (FGF), and tumor necrosis factor-α (TNF-α), have been found to promote the synthesis of PAF in cancer cells." (PMID 40033370, 2025). "Moreover, activation of common pathways in some cancers, such as KRAS pathway, activation of IL6-JAK-STAT3/STAT5 pathway and activation of TNFα signaling pathway via NFkB were remarkably correlated." (PMID 39925804, 2025). "A retrospective multicenter observational study suggested that TNF-inhibitors may be more effective for treatment of ICI-IA, but there was a trend toward increased cancer progression." (PMID 40170117, 2025). "Our research contributes to the expanding field of cancer therapies by analyzing immune changes in the peripheral blood at the single-cell level in patients treated with the oncolytic adenovirus TILT-123 coding for IL2 and TNFα." (PMID 40211048, 2025). "Deacetylated KLF5 increased TNF-α secretion by tumor cells, which in turn drove iCAFs toward an earlier, high-FGF9–secreting state, establishing a TNF-α–FGF9 reinforcing loop with Krt4+ cancer cells." (PMID 41514658, 2025).
cancer (continued). "A major contribution of TNF-α to BC progression is the induction of EMT and cancer stemness." (PMID 40868199, 2025). "Likewise, in the MDCa@RBC‐Alipo treatment group, significantly elevated levels of serum cytokines such as TNF‐α, IL‐6, and IL1‐β, which play crucial roles in cellular immunity against cancer, were observed." (PMID 40289661, 2025). "Moreover, recent evidence also suggests that cancer cells hijack RIPK1 (i.e., stabilise its scaffold function) to enhance cell survival, induce TNF insensitivity, and confer resistance to immunotherapy." (PMID 41334873, 2025). "Moreover, various pro‐inflammatory markers i.e., IL‐1, IL‐6, TNF‐α, IFN‐γ, TGF‐β and growth factors (VEGF, EGF, IGF‐2) are also involved in cancer progression." (PMID 40755497, 2025). "The addition of TNFα-neutralizing antibodies did not reduce the inhibition of muscle differentiation induced by cancer patient serum." (PMID 40283883, 2025). "It is assumed that IL-1, TNFα, and IFN-β may also synergistically promote immune responses, thereby improving treatment outcomes, especially in cancer and infectious diseases." (PMID 41460922, 2025). "P. gingivalis induces the secretion of many cancer-contributing chemokines and cytokines, including Interleukin (IL)-1β, IL-6, IL-8, transforming growth factor (TGF)-β1, epidermal growth factor (EGF), and tumor necrosis factor alpha (TNF-α)." (PMID 41471188, 2025). "Furthermore, interleukin (IL)-17, IFN-γ, and tumor necrosis factor alpha (TNF-α) can independently control PD-L1 by activating AKT, nuclear factor-κB (NFκB), and extracellular regulated protein kinase (ERK) signaling in cancer cells." (PMID 41008336, 2025). "Although some crucial pathways (e.g., MAPK, Apoptosis, ERBB, JAK-STAT) were not top-ranked, core genes within these pathways (AKT1, EGFR, CASP3, TNF, SRC) showed high connectivity in the PPI network, reinforcing their relevance to the anti-cancer mechanisms of Siegesbeckiae Herba constituents." (PMID 41006588, 2025). "TNF-α has been shown to contribute to the aggressiveness of TNBC by activating growth-promoting pathways that induce invasion and metastasis, and the generation of cancer stem cells that promote relapse." (PMID 41439881, 2025). "The intratumoral administration of TNF-α and IFN-γ exhibits pan-cancer therapeutic efficacy." (PMID 40721869, 2025). "Moreover, several regulator proteins, growth factors, and cytokines, like IFN-γ, EGF, and TNF, exert their oncogenic effect by upregulating MMP-9,30, 31, 32, 33 suggesting its central role in cancer progression." (PMID 41273852, 2025). "Studies have not found a direct relationship between anti-TNF drugs and the development of recurrence or de-novo cancer." (PMID 40933968, 2025). "The study encompassed 3465 IBD patients who had not been exposed to TNF-α antagonists, among whom 6.7% developed cancer, and 81 patients who had been exposed to these antagonists, with 1.8% developing cancer." (PMID 39968296, 2025). "Furthermore, isorhamnetin suppresses the NF-κB pathway activation, which decreases pro-inflammatory cytokines such as IL-6 and TNF-α and decreases EMT, avoiding cancer cell migration and metastasis." (PMID 40806510, 2025). "Coculture killing assay showed ASPG-OE CAR-T cells exhibited increased killing efficacy against ASNS-OE cancer cells by enhancing the expression of granzyme B, interferon gamma, and tumor necrosis factor alpha, whereas ASPG-knockout (KO) CAR-T cells showed decreased cancer cell lysis efficiency." (PMID 40808257, 2025). "Moreover, adipose tissue secretes various adipokines, including tumor necrosis factor (TNF)-α, interleukin (IL)−6, leptin, and insulin-like growth factor (IGF-1), which are thought to have pathological effects in various cancers." (PMID 40624408, 2025). "TNF-α enhances YAP/TAZ expression via NF-κB or directly inhibits LATS activity, thereby increasing YAP/TAZ nuclear localization and promoting inflammation-driven cancer cell invasion and metastasis." (PMID 41450917, 2025).
cancer (continued). "While individuals without cancer and patients with cancer treated with CT alone harbor monofunctional spike-specific CD4 T cell producing TNF, the majority of monofunctional CD4 T cells in patients treated with IT alone or in combination with CT produce IFNγ." (PMID 39257577, 2024). "Our results showed that IL-6, IL-12, TNF-α, and NF-κB increased significantly in the AOM group for both normal diet and HFD but decreased significantly when treated with PB showing that PB has anti-inflammatory effects in cancer cells." (PMID 39845239, 2024). "Anti-PD1 can supply these necessary ligands by promoting TNF production, thereby sensitizing cancer cells to cell death in the absence of RIPK1." (PMID 39681571, 2024). "Interferon (IFN), interleukins (ILs), tumor necrosis factor (TNF)‐like cytokines, chemokines, growth factors such as transforming growth factor (TGF), and vascular endothelial growth factor (VEGF) play key roles in cancer development." (PMID 39453820, 2024). "Change of the culture medium in combination with the pro-inflammatory cytokine tumor necrosis factor-alpha (TNF-α) evoked a time-, and dose-dependent enhancement in UPE in both non-cancer and cancer cell lines, with UPE increasing significantly more in cancer than in non-cancer cells." (PMID 39357824, 2024). "Furthermore, our pan-cancer comparison of TCGA data reveals that HNSCC and other squamous cancers harbor the highest frequency of genomic alterations in these TNFα/NF-κB/cell death pathways." (PMID 39392349, 2024). "Moreover, differential genes were also enriched in critical cancer-related signaling pathways, including the PI3K-Akt, TNF, and NF-kappa B signaling pathways." (PMID 38911368, 2024). "Additionally, they secrete cytokines like interferon-gamma (IFN-γ) and tumor necrosis factor-alpha (TNF-α), further contributing to cancer cell demise." (PMID 38791916, 2024). "Overall, although preclinical and early clinical trials have not yet successfully targeted TNF-α in cancer treatment, it remains a promising target for future research." (PMID 39195299, 2024). "Tumor necrosis factor (TNF)-related apoptosis-inducing ligand (TRAIL) is a member of the TNF protein superfamily and was initially identified as a protein capable of inducing apoptosis in cancer cells." (PMID 39451194, 2024). "Shared inflammatory pathways, such as their regulation by TNF-α, may connect MAN1A2 to immune-related mechanisms common to both cancers and RLS." (PMID 39770468, 2024). "The scRNA-seq data from four different cancer cell lines (A549, DU145, MCF7, and OVCA420) revealed that signaling pathways known to drive EMT- like TGFβ1, EGF, and TNF- converge on NF-κB and FOSL1, before initiating the expression of typical EMT master regulators such as STAIL, TWIST, and ZEB." (PMID 38856747, 2024). "Moreover, alloferon enhances NK cells’ ability to eliminate cancer cells and virally infected cells through two main mechanisms: 1) increasing the production of cytokines IFN-γ and TNF-α and 2) secretion of lytic/exocytotic granule." (PMID 38434708, 2024). "The function of M2 macrophages in promoting tumor development depends on the proinflammatory cytokines, such as TNF-α, IL-6, and IL-11, which can activate the nuclear factor–κB (NF-κB) and signal transduction and activator of transcription 3 (STAT3) pathway in cancer cells." (PMID 38605951, 2024). "According to KEGG analysis, CFF-1 could have anti-cancer effects against PCa by regulating cancer cell proliferation and survival through PI3K-Akt, HIF-1, TNF, EGFR-TKI resistance and PD-1 checkpoint signaling pathways." (PMID 38484140, 2024).
cancer (continued). "With the discovery that tumor necrosis factor (TNF) can kill cells, and the identification of its receptor, TNF Receptor 1, the search for therapeutics that induce apoptosis (programmed cell death) in cancer cells began." (PMID 40061208, 2024). "Kyoto Encyclopedia of Genes and Genomes (KEGG) pathway analysis revealed that OTUB1 is involved in various important signaling pathways, such as transcriptional regulation, PI3K-AKT signaling pathway, cancer-related pathway, TGF-β signaling pathway, TNF pathway, Hippo signaling pathway and so on." (PMID 39113709, 2024). "TNF-α is reported to be increased in over 80% of all CRC patients, positively correlates with increased disease stage, and forms a mechanistic link between inflammation and cancer." (PMID 39310770, 2024). "An IAP antagonist alone, such as SM-164, AT-406, or BV6, which effectively degrades IAPs, does not effectively induce cancer apoptosis, but enables TNFα to strongly induce cancer cell apoptosis." (PMID 39105847, 2024). "The interaction of TNF-α with TNFR2 can result in the activation and differentiation of various immune cells whose normal function is to regulate excessive immune response; however, these mechanisms fail in many cancers, including BC." (PMID 39609700, 2024). "Cancer cells lacking NF-κB activity show increased sensitivity to TNF-α and chemotherapeutic agents, making NF-κB a promising target for cancer therapy." (PMID 39519572, 2024). "Interestingly, the basal levels of TNF-α were increased when the cancer cells were treated with CAF CM or cocultured with CAFs, suggesting a potential role of the crosstalk between cancer cells and CAFs in TNF-α secretion." (PMID 38781024, 2024). "For example, Frank Cichocki and others demonstrated that in the existence of GSK3 inhibitor CHIR99021, the production of tumor necrosis factor-α (TNF-α) and interferon-γ (IFN-γ) by NK cells was significantly increased, which enhanced NK cytotoxicity, fueled immunotherapy of cancer." (PMID 38755125, 2024). "Conversely, the effects of reduced TNF-alpha on cancer are not straightforward, as they vary by cancer type." (PMID 39518143, 2024). "Consequently, inflammatory molecules such as the interleukin 2 (IL‐2) and tumor necrosis factor alpha (TNF‐⍺) are released, simulating cancer death through necrosis or apoptosis." (PMID 38894611, 2024). "TNFα alone does not effectively kill cancer cells because it markedly increases protein levels of cIAP1 and cIAP2 by cancer cells." (PMID 39105847, 2024). "HIF-1α promotes cancer cell growth and angiogenesis via hypoxic or non-hypoxic pathways, and TNF R1 is involved in TNF signaling pathways, which regulate cell death." (PMID 39382942, 2024). "The natural killer (NK) cells are the key barriers against cancers, and they directly interact with malignant cells for their killing through proteolytic granzymes and secretion of cytokines such as IFN-γ, MIPs, IL-8, IL-10, and TNF-α." (PMID 39014491, 2024). "Furthermore, alloferon improved NK cells’ potency against cancer cells by upregulating the expression of NK-activating receptor 2B4 and increasing the production of IFN-γ, TNF-α, and granule exocytosis." (PMID 38434708, 2024). "Infiltrated T cells releases TNF-α and IFN-γ to kill cancer cells." (PMID 38813211, 2024). "Moreover, anticancer immunotherapies, such as immune checkpoint blockade (ICB), elevate TNF levels in the TME, and ICB efficiency depends on cytokine-induced senescence in cancer cells." (PMID 38612842, 2024). "Secreted by TAMs, IL-1β, IL-8, TNF-α, and TGF-β promote EMT in cancer cells." (PMID 39516356, 2024). "This is consistent with the co-culture results that showed a lack of TNFα production with only cancer cell-specific STING activation by Fc-mutant HER2-ADC." (PMID 38992037, 2024).